CD4 (CD4 molecule)
Diseases named in the same sentence as CD4 in open-access papers (continued):
Sharing a sentence is not in itself a finding about the gene and the disease.
depression (continued). "A previous study reported that CD4+ T cells are positively related to anxiety and depression in patients infected by the human immunodeficiency virus." (PMID 36386524, 2022). "Immune cell infiltration analysis showed that levels of inflammatory cells, such as CD4 T cells, were significantly increased in depressed rats and were significantly correlated with the depression hub genes." (PMID 35480327, 2022). "A study revealed that dramatic mitochondrial fission in CD4+ T cells contributes to anxiety and depression in mice." (PMID 36386524, 2022). "Depression seems to be a risk factor for incomplete short-term HIV viral suppression among HIV-infected patients, and therefore poor CD4 cell count recovery." (PMID 36298842, 2022). "With regards to the HADS depression score, the CD4+ effector memory population negatively correlated in controls (r=-0.64, p=0.03) but not in FD." (PMID 36685573, 2022). "This study further evaluated the relationship of therapeutic strategies with anxiety, depression, cognitive impairment, CD4+ T cells, and corresponding inflammatory cytokines in elderly gastric cancer patients." (PMID 36386524, 2022). "The suggested mechanism of action is fewer circulating CD4+ T-cells and a reduction in natural killer cell cytotoxic responses of lymphocyte proliferation in elderly patients with clinical depression." (PMID 36201406, 2022). "The correlates of anxiety and depressive disorders included age of the child, caregiver' psychological distress, caregivers' age, child-caregiver relationship, child's current CD4 count, and hospital admissions." (PMID 35572346, 2022). "Correlates of “anxiety and depressive disorders” included age of the child, caregiver' psychological distress, caregivers' age, child-caregiver relationship, and child's current CD4 count (aOR1.00, 95% CI 1.02–1.05; p = 0.021)." (PMID 35572346, 2022). "Sleep disturbances were associated with less income, higher CD4 counts, antiretroviral treatment (ART) initiation, exercise, depression, and higher stress levels." (PMID 34295273, 2021). "PLHIV with depression had higher prevalence of underweight BMI (13.1% vs. 4.7%, p<0.01) and a 67 cells/mm3 lower median CD4 T-cell count (vs. 262 cells/mm3 vs. 329 cells/mm3, p<0.01) compared to those without depression." (PMID 33490927, 2021). "Secondary outcomes were adherence and depression over 4‐, 8‐ and 12‐month follow‐ups, proportion of participants with undetectable viremia and continuous CD4 cell counts at 12 months." (PMID 34708929, 2021). "The number of participants with CD4 count of > 500 cells/mm3 who reported at least a slight problem on the anxiety/depression dimension was found to be 39 (28.3%)." (PMID 33468153, 2021). "Rapid progression occurred in 186/400 (46.5%) of the patients, and was more prevalent in those with HSV-2 coinfection, depression, low CD4+ T cell counts, and a high VL at baseline, and in those with a specific range of baseline routine blood test results." (PMID 34367176, 2021). "Case-control studies have implicated multiple other pro- and anti-inflammatory markers in depression and immunophenotyping work suggests that patients exhibit increased monocyte, CD4+ T cell, and neutrophil counts." (PMID 34135474, 2021). "Epigenetic processes are important in relation to the availability of genetic information at the cytokine gene loci in CD4 + T cells, whose presence, as confirmed by research, has an impact on the development of depression in later years." (PMID 33385173, 2021). "The expressions of TLR2 and TLR4 on Th17 (IL-17+CD4+ T cells)/Tc-17 (IL-17+CD8+ T cells) were significantly upregulated in MS with major depressive disorder (MDD) compared with MS." (PMID 34790205, 2021). "In contrast, 60 (75%) of participants with CD4 count of 100–200 cells/mm3 reported having a slight or more problems on the anxiety/depression dimension." (PMID 33468153, 2021).
depression (continued). "An important element in the neuroimmunological background is also the fact that CD4 + T cells in patients diagnosed with depression are subject to spontaneous accelerated apoptosis." (PMID 33385173, 2021). "The finding of current study confirmed the findings of previous studies that some factors affect PLWHA's QoL: coinfection, availability, ARV, compliance with ARV, CD4 number, social support, occupation, gender, stigma, and depression rate." (PMID 33509063, 2021). "Secondary outcomes include HIV viral load and CD4 cell count at the 12-month assessment as well as adherence (Wisepill) and depression (HAM-D) over follow-up (4-, 8-, and 12-month assessments)." (PMID 32012114, 2020). "We chose CD4 cells, also called T4 cells, because they are immunological “helper” cells that effectively respond to treatment for depression in women." (PMID 32434503, 2020). "Based on the results of bivariate analyses as well as prior evidences, the following covariates were included into penalized logistic regression model: age, gender, marital status, depression symptoms, anxiety symptoms, latest CD4 count, and efavirenz use." (PMID 32448151, 2020). "On the other hand, less symptomatology, less depression and anxiety and better quality of life, and greater spiritual well-being is related to higher CD4 response." (PMID 32434503, 2020). "Depression in common among PLWH and is associated with declining CD4 counts in previous studies (Olisah, Adekeye, & Sheikh, 2014)." (PMID 33777501, 2020). "The variables significantly associated with non-adherence to ART in the univariate analysis included methamphetamine use during the prior three months, income level, depressive disorder, CD4 count, and plasma viral load." (PMID 32346081, 2020). "In our study, predictors of poor adherence to ART drugs were depression, anxiety disorder and low CD4 count which have been reported in similar studies." (PMID 31692880, 2019). "The findings reflect the importance of evaluating for depression in PLWHA, especially in high-risk groups such as patients presenting for their initiation visit or patients with a CD4 count of 50 or less." (PMID 31402989, 2019). "The patients with more depression symptoms, have the low rate of CD4 cells and probably have the low rate of adherence to the diet compared to those patients with more PTSD symptoms and patients with more symptoms in both disorders (depression and PTSD)." (PMID 30847322, 2019). "More symptoms of depression in HIV patients are associated with lower adherence to the medication diet and low rate of the CD4." (PMID 30847322, 2019). "This study indicates a good adherence in majority of the patients but a small proportion with predictors of poor adherence to anti-retroviral therapy which were depression, anxiety disorder and low CD4 count." (PMID 31692880, 2019). "The significant difference in the CD4+/CD8+ ratio was observed only in patients with depression compared to healthy people (7, 61 ± 0, 68 vs. 3, 84 ± 0, 46, p = 0, 002689, ANOVA with post-hoc test)." (PMID 30971748, 2019). "The study identifies the need for evaluating for depression in PLWHA, particularly in high-risk groups such as patients at their first or initiation visit or patients with a CD4 count of 50 or less." (PMID 31402989, 2019). "Logistic regression indicated that predictors of poor adherence were depression, anxiety and low CD4 counts." (PMID 31692880, 2019). "Patients in depression had significantly lower percentage of CD3+CD4+ cells compared to healthy control (62, 33 ± 2, 64 vs. 75, 38 ± 1, 79, p = 0, 007804, ANOVA with post-hoc Tukey test)." (PMID 30971748, 2019). "Participants who had a lower CD4 cell count at the first time of receiving ART were more likely to have depression compared to those with a CD4 cell count ≥500." (PMID 30562949, 2018).
depression (continued). "The intervention lasted for 3 months, and all participants were assessed for their medication adherence, presence of depression, quality of life (QoL), and CD4 (cluster of differentiation 4) counts." (PMID 30181109, 2018). "The two groups were similar in terms of sociodemographic, behavioral, and clinical characteristics except gender, ethnicity, employment status, time on ART, CD4 count, and depression." (PMID 30161177, 2018). "Variables such as; availability of reminder, substance use, malnutrition, dietary diversity, CD4 count, depression symptom, adverse effect of ART and duration on ART were reported as a determinant factor for non-adherence to ART." (PMID 28331527, 2017). "In multivariable analysis variables, such as duration of treatment, ART adverse effect, substance use, living condition, depression, CD4 cell count and dietary diversity were found to be independent determinant factors with non-adherence to ART." (PMID 28331527, 2017). "Average CD4 count increased from 32 cells/μL to 80 cells/μL (P < 0.001) and average depression scores decreased from 19 to 16 (P = 0.04)." (PMID 28606065, 2017). "Results this study aimed to investigate the relationship between the antiretroviral medication adherence and the rate of CD4 with depression and social support in the people with HIV." (PMID 27157183, 2016). "We collected data on the history of ART initiation, CD4+ cell count monitoring, socio-demographic variables, perceived family support (measured with 10-item Nepali Family Support and Difficulty Scale), depression, and HIV symptom burden." (PMID 27369221, 2016). "This study aimed to investigate the relationship between the antiretroviral medication adherence and the rate of CD4 with depression and social support in the people with HIV." (PMID 27157183, 2016). "In another study carried out by Horberg (2008), depression treatment was consistent with increase in the rate of CD4." (PMID 27157183, 2016). "Approximately, 44.7% had a CD4 count of less than 500/cm3, 22.3% were co-infected with TB, and 16.3% had a probable mild to major depression based on the PHQ 9 scores." (PMID 27548753, 2016). "Current CD4 cell count was within the normal range, and 37 % of this sample met criteria for depression based on the standard cut-offs of the screening instruments." (PMID 26563353, 2015). "The other variables in the multivariate model included sex, age, study visit, WHO stage, education level, income per month, depression, employment status, alcohol use, social support and baseline CD4 count." (PMID 26216221, 2015). "In both expected outcomes (CD4 and depression), age seems to contribute to greater differences in their means, disfavoring disproportionately Hispanics." (PMID 25560348, 2014). "To measure disparities across individuals, we used the Oaxaca Decomposition approach to assess physical health (CD4 counts) and mental well-being (depression) disparities experienced by Hispanics in a cross-section of HIV-positive adults age 50 and older." (PMID 25560348, 2014). "But the present study finding is similar with reports from Uganda; controlling for sociodemographic variables, their analysis showed that those respondents who have CD4 cell counts <50 cells/microliter were more likely to develop depression." (PMID 24852246, 2014). "In conclusion, CD4+CD25+ Treg cells play a role in the manifestation of depression-like behaviors, immune alterations and changes in the neurochemical status." (PMID 22860054, 2012). "Consistent with these previous reports, the immune imbalance in major depression patients was not only characterized by changes in cytokine levels, but also by a decrease in the CD4+CD25+ Treg cell population in peripheral blood lymphocytes." (PMID 22860054, 2012). "Further work to disentangle the relationships between major depressive disorder and low CD4 counts is equally needed." (PMID 23209556, 2012).
depression (continued). "The third was to explore the association between performance on the IHDS and important variables, such as depression, age, education and current CD4 count." (PMID 20406460, 2010). "We also compared performance on the IHDS with performance on tests of verbal learning/memory and processing speed, and investigated the association between performance on the IHDS and such variables as depression, age, level of education and CD4 count." (PMID 20406460, 2010). "As individuals improved immunologically with an increase in the CD4 count, there was a decrease in the symptoms of cognitive impairment and depression." (PMID 20537129, 2010). "Further, we found that the relationship between depression and rural residency persisted when stratified by CD4 count strata." (PMID 19265529, 2009). "Our finding that depression prevalence remains elevated for rural HIV patients across multiple CD4 strata supports this possibility." (PMID 19265529, 2009). "While the overall number of participants with depression appeared lower among those with CD4 ≤ 200 cells/ml, the percent of those listing depression out of those with any diagnosis remained close to 92.5% across all strata." (PMID 15350202, 2004). "Metabolic abnormalities in peripheral CD4 + T cells may also induce purine metabolism dysfunction, leading to anxiety, depression, and deficits in social behavior." (PMID 41458124, 2025). "In addition, the relationship between IPV and lower CD4 + cell counts is fully mediated by depression." (PMID 40133939, 2025). "This was confirmed with multivariate, stepwise, linear regression with IL-6 as the outcome variable and BRS-V, age, ACB score, CD4+, sex, Charlson score, and diagnoses of anxiety and depression as the predictors; the final model retained BRS-V (p=0.012) and age (p=0.028)." (PMID 39464041, 2025). "In addition, individuals with a CD4 count of less than 200 cells/mm3 had 2.4 times higher odds of suffering depression than those with a CD4 count greater than or equal to 200 cells/mm3 (AOR=2.4: 95% CI, 1.78, 8.23)." (PMID 40485941, 2025). "Specifically, of the studies included in the analysis of each subtype, there was a marked increase in the mean absolute counts of white blood cells, granulocytes, neutrophils, monocytes, CD4 T cells, natural killer cells, B cells, and activated T-cells in depression, compared to controls." (PMID 38665228, 2024). "The analysis of DEGs may provide clues on the role and mechanism of CD4+ naive T cells in depression." (PMID 38867657, 2024). "In addition to increased innate immune response, cell-mediated adaptive immune activation also occurs in patients with depression, and one of the key features of this activation is increased CD4+/CD8+ T cells ratio." (PMID 38742123, 2024). "Among other findings, an increase in thymus- and spleen-derived naïve CD4+ T cells can be observed in rats during the period of chronic restraint stress exposure, whereas splenomegaly and thymic atrophy has been observed in animal models of depression." (PMID 39681901, 2024). "For example, we note that depression management can boost HIV patients' CD4 count thus reducing viral load, and that this may lower the need for frequent visits to health facilities, consequently cutting down on health workers' work load." (PMID 36704236, 2023). "In our study, depression was associated with non-psychiatric outcomes even when CD4 count and viral load are held constant." (PMID 37084105, 2023). "Also, patients with depression and hypomania had a reduced percentage of CD4+ and CD8+ cells compared to healthy people." (PMID 37662097, 2023). "Another possible explanation is that male individuals may present significantly higher levels of immune-inflammatory markers (e.g., CD3, CD4, and CD8), while female individuals may demonstrate relatively greater risk for inflammation-related depression." (PMID 38012724, 2023).
depression (continued). "Therefore, this study aimed to evaluate the relationship between CDC42 and CD4+ T cells, as well as their correlations with anxiety, depression, and cognitive impairment in stroke patients." (PMID 37703110, 2023). "In addition, the relationship between IPV and lower CD4 + cell count was fully mediated by depression." (PMID 38168236, 2023). "Later-life depression females also showed a downregulation of CD4+ T cell-related genes." (PMID 35844577, 2022). "Thus, we intended to determine the crucial role of CD4+ Th17 cells in the development of specific subtypes of depression and unravel the underpinnings of their pathogenetic effect." (PMID 35836182, 2022). "Immune cells such as B cells naive, T cells CD8, and mast cells resting had a significantly higher expression in patients in the depression group, whereas B cells memory and T cells CD4 memory resting showed a significantly higher expression in patients in the normal control group." (PMID 36325528, 2022). "This subtype of CD4+ T cells may be a promising therapeutic target for the early treatment of stress-induced depression." (PMID 35836182, 2022). "In conclusion, we identified three laboratory parameters, namely CD4+/CD8+ T cell ratio, albumin concentration, and M%, that were associated with the severity of the depressive disorder, and constructed a novel joint index to discriminate disease severity more objectively and sensitively." (PMID 35395781, 2022). "Based on the importance of identifying biochemical correlates, this study investigated GSH levels, CD4 and CD8 lymphocyte counts, and their associations with perceived stress, anxiety and depression symptoms, self-esteem, and socio-familiar support in young adults without a prior clinical diagnosis." (PMID 35069302, 2021). "In the human setting, CD4+CD25+ Tregs are found decreased in patients with major depression." (PMID 34367160, 2021). "In addition, depression can harm the immune system by decreasing its cluster of differentiation 4 (CD4) cells, perpetuating a cycle." (PMID 34277275, 2021). "Our recent findings show an increased frequency of CD4+ T cells in adults with depression." (PMID 34927102, 2021). "The development of fatigue was higher among anemic study participants 119 (87.5%), those with CD4 count of > 200 (67, 73.6%), those who had depression 226 (79.6%), and those participants who had physical disability (11, 84.6%) compared with their comparison groups." (PMID 32295546, 2020). "An indirect relationship has been shown to exist between CD4 count and depression." (PMID 32818041, 2020). "Additionally, the growing evidence suggests the significant role of immunological factors, such as CD4 cells, on the pathophysiology of depression development, particularly among patients with chronic illnesses." (PMID 32742296, 2020). "Inversely, a low CD4 count can be an indicator of untreated depression." (PMID 32818041, 2020). "ART adherence and associated factors: multivariate analysis on the association of ART adherence against predictors such as; gender, age, CD4 count, viral load, insomnia index, depression score and anxiety score were carried out using binary logistic regression." (PMID 31692880, 2019). "However, our data demonstrates a disconnect between central symptoms, such as anxiety, depression, somatization and CD4+ T-cell activation." (PMID 30842618, 2019). "Untreated depression likely has a negative effect on immunological response and viral suppression, being associated with greater declines in CD4 counts and increases in viral load." (PMID 31317365, 2019). "Severe depression was associated with lower CD8-positive cells in a large-scale meta-analysis among medically healthy persons, and as severity of depression may decrease after medication, CD4/CD8 ratio is correlated with the severity of depression." (PMID 30065772, 2018).